LRRC53 (leucine rich repeat containing 53)
Tractability: Antibody: UniProt predicts a signal peptide or a membrane-spanning region; its Gene Ontology location is reachable by antibodies, with medium confidence. PROTAC: ubiquitination databases record sites on it.
Gene: Protein-coding gene on chromosome 1 (74,469,376 to 74,512,611, reverse strand). Ensembl gene ENSG00000162621.
Subcellular location: Membrane
Gene Ontology:
Cellular component: plasma membrane; membrane
Homologues: Orthologues: chimpanzee LRRC53 (98% identical), macaque LRRC53 (93% identical), Drosophila melanogaster CG6749 (8% identical), Drosophila melanogaster trn (8% identical), Caenorhabditis elegans lron-15 (8% identical), Drosophila melanogaster caps (8% identical), zebrafish chadla (7% identical), Drosophila melanogaster CG32055 (6% identical). Paralogues in human: LRRC32 (7% identical), TLR5 (7% identical), TLR7 (7% identical), TLR8 (7% identical), TLR4 (7% identical), NRROS (7% identical), TLR3 (7% identical), TLR6 (6% identical), CD180 (6% identical), TLR1 (6% identical), TLR2 (6% identical), VASN (6% identical), and 10 more.